SPATS2 (spermatogenesis associated serine rich 2)
Diseases named in the same sentence as SPATS2 in open-access papers:
SPATS2 is named in the same sentence as 13 diseases in open-access papers, as found by Europe PMC text mining. Sharing a sentence is not in itself a finding about the gene and the disease. The quoted sentences say what the papers report.
liver cancer (7 papers, 2020 to 2023). An epithelial or non-epithelial malignant neoplasm that arises from the liver. "In liver cancer, miR-145-5p was reported as an inhibitor of cell proliferation by negatively targeting the oncogene Spermatogenesis associated serine-rich 2 (SPATS2) and Kruppel-like factor 5 (KLF5)." (PMID 36214767, 2022). "Recently, SPATS2 expression was reported to be a diagnostic and prognostic biomarker in liver cancer." (PMID 33391405, 2021). "Next, we obtained the SPATS2 mRNA expression-associated genes in liver cancer." (PMID 36631750, 2023). "Consistent with previous results, SPATS2 expression acts as an oncogene, which could be served as a diagnostic and prognostic biomarker in liver cancer." (PMID 36631750, 2023). "Recently, SPATS2 is reported to be a diagnostic and prognostic biomarker in liver cancer." (PMID 36631750, 2023). "SPATS2 is also highly expressed in liver cancer and may be a new diagnostic and prognostic biomarker of liver cancer." (PMID 36147484, 2022). "Interestingly, high expression of SPATS2 is associated with poor prognosis in liver cancer as well." (PMID 33411682, 2020). "In recent years, SPATS2 has been reported to contribute to the tumorigenesis of multiple malignancies, including liver cancer." (PMID 36631750, 2023). "TCGA results showed that the methylation level of SPATS2 promoter region was decreased in liver cancer tissue." (PMID 35077478, 2022). "SPATS2 expression patterns in patient samples were derived from TCGA database, SPATS2 was more highly expressed in human primary liver cancer tissue (n = 369) than in normal human liver tissue (n = 50)." (PMID 35077478, 2022). "TCGA database analysis revealed that upregulated SPATS2 was correlated with higher expression of SNHG5 in liver cancer." (PMID 35077478, 2022). "Gene Set Enrichment Analysis (GSEA) revealed that the liver cancer survival gene set was enriched in the SPATS2 high expression group." (PMID 33037180, 2020). "Moreover, SPATS2 protein level was upregulated in LIHC based on the protein expression results of HPA database in liver cancer." (PMID 36631750, 2023). "Thus, SPATS2 plays an important role in the recruitment and regulation of some immune infiltrating cells in liver cancer." (PMID 36631750, 2023). "Moreover, Kaplan-Meier analysis (log-rank test) demonstrated that the elevated SPATS2 was related to poor overall survival of liver cancer patients (p<0.0001)." (PMID 35077478, 2022). "Moreover, wound healing assays showed that the metastatic ability was reduced, indicating that SPATS2 promotes the migration of liver cancer cells." (PMID 35077478, 2022). "To verify whether SNHG5 promotes the expression of SPATS2 in human liver cancer, we performed SNHG5 gene knockdown and overexpression experiments in HepG2 cells." (PMID 35077478, 2022). "For liver cancer, recent reports have noticed the tumor-suppressive effects of miR-145-5p in either cholangiocarcinoma or HCC by targeting different mRNAs, like CDCA3, and SPATS2, and involved in cell proliferation, apoptosis, or metastasis." (PMID 36214767, 2022). "Although an increasing number of studies have elucidated the biological function of SNHG5 in liver cancer, the function and regulatory mechanism of SNHG5 in SPATS2 expression has not been reported." (PMID 35077478, 2022).
colorectal cancer (6 papers, 2020 to 2023). A primary or metastatic malignant neoplasm that affects the colon or rectum. "It has been reported that SPATS2 serves a tumorigenic role in several cancers, such as esophageal squamous cell carcinoma, colorectal cancer, prostate cancer, and HCC." (PMID 36631750, 2023). "Damas and colleagues showed that lncRNA-SNHG5 promotes colorectal cancer cell survival by counteracting STAU1-mediated SPATS2 mRNA destabilization." (PMID 34163032, 2021). "Although accumulating studies have revealed the potential oncogenic function of SPATS2 in colorectal cancer and squamous cell carcinoma, the role of SPATS2 in HCC has not been investigated so far6,7." (PMID 33037180, 2020). "Moreover, SPATS2 promotes lncRNA SNHG5-mediated survival of colorectal cancer cells through pro-proliferative and anti-apoptotic effect." (PMID 36631750, 2023). "In colorectal cancer, SNHG5 interacts with the SPATS2 (spermatogenesis associated serine rich 2) and increases its stability by blocking the mRNA degradation in the cytoplasm, caused by STATS2 mRNA interaction with STAU1 (staufen double-stranded RNA binding protein 1)." (PMID 32318335, 2020). "SPATS2 participated in the process of lncRNA SNHG5-mediated colorectal cancer cell survival." (PMID 33037180, 2020). "SNHG5 promotes colorectal cancer by stabilizing its target SPATS2 via inhibiting SMD39." (PMID 32527996, 2020). "SPATS2 is dysregulated in a few types of cancers such as HCC, squamous cell carcinoma, and colorectal carcinoma (CRC)." (PMID 35077478, 2022).
hepatocellular carcinoma (5 papers, 2020 to 2025). A malignant tumor that arises from hepatocytes. "MiR 145 5p also inhibits SPATS2 expression, whose protein product promotes proliferation, metastasis, and invasion in multiple cancers, including hepatocellular carcinoma." (PMID 41465470, 2025). "SPATS2 negatively regulates by miR-145-5p and results in promoting hepatocellular carcinoma progression through regulating cell cycle." (PMID 36631750, 2023). "A recent study indicated that SPATS2 promotes hepatocellular carcinoma progression by regulating the cell cycle." (PMID 35077478, 2022). "Collectively, these mechanisms allow circ0001955 to restore the carcinogenic activity of ARF6, SPATS2, TRAF6, and MAPK11 in chronically HCV-infected hepatocytes, promoting the initiation and progression of hepatocellular carcinoma." (PMID 41465470, 2025). "However, there is no systematic study on the differential expression, prognostic significance, epigenetic regulation, immune infiltration of SPATS2 in hepatocellular carcinoma (HCC)." (PMID 36631750, 2023). "The molecular function of SPATS2 in hepatocellular carcinoma (HCC) is still not fully understood." (PMID 33037180, 2020).
squamous cell carcinoma (4 papers, 2020 to 2021). A carcinoma arising from squamous epithelial cells. "SPATS2 is a novel candidate biomarker for squamous cell carcinoma." (PMID 33411682, 2020). "Recent research has shown that SPATS2 is strongly expressed in squamous cell carcinoma but rarely in non-lepidic AD." (PMID 33936227, 2021).
cholangiocarcinoma (2 papers, 2020 to 2022). A carcinoma that arises from the intrahepatic biliary tree (intrahepatic cholangiocarcinoma) or from the junction, or adjacent to the junction, of the right and left hepatic ducts (hilar cholangiocarcinoma). "However, CD36, GGCX, UBASH3B, DBN1, PTTG1, CCNA2, and SPATS2 are found in other tumors to regulate tumor progression, which may also regulate cholangiocarcinoma progression and affect the recurrence of CCA." (PMID 32071556, 2020).
Hypertension (1 paper, 2022). The presence of chronic increased pressure in the systemic arterial system. "Among these genes, Spermatogenesis-Associated Serine-Rich 2 (SPATS2L) revealed 21 hypertension-associated SNPs, of which 9 SNPs were ≥4 log-p value." (PMID 35629146, 2022).
lung carcinoma (1 paper, 2021). "The sensitivity and specificity of CLCA2, SPATS2, ST6GALNAC1, and Adipophilin in adequate subtyping of poorly differentiating lung cancer and reaching accurate diagnosis was 100%." (PMID 33936227, 2021). "The combination of biomarkers of CLCA2, SPATS2, ST6GALNAC1, and Adipophilin may lead to an appropriate subtyping of lung cancer and reaching accurate diagnosis with the highest sensitivity and specificity." (PMID 33936227, 2021).
tumor (12 papers, 2016 to 2025). "Association analysis between SPATS2 up-regulation in tumor and clinicopathologic characteristics of HCC patients." (PMID 33411682, 2020). "The univariate analysis identified that Child–Pugh (p = 0.029), vascular invasion (p = 0.003), TNM stage (p = 0.000), tumor size (p = 0.004), tumor multiplicity (p = 0.019), and SPATS2 expression (p = 0.033) were significantly associated with survival." (PMID 33037180, 2020). "Tumor suppressor action by inhibit the expression of SPATS2 and increased p21 and p27 which inhibits cell proliferation and migration." (PMID 41465470, 2025). "To further validate the function of SPATS2 in HCC, we comprehensively analyzed gene expression, prognosis, epigenetic regulation, and tumor immune cells infiltration of SPATS2 in HCC." (PMID 36631750, 2023). "By comparing tumor with adjacent tissue, we found that SPATS2 level was widely expressed in B cells, macrophage, and DC cells." (PMID 36631750, 2023). "In our study, SPATS2 was found for the first time to be highly positively correlated with the tumor infiltration of Tregs, B cell, macrophage, and DC cells in HCC." (PMID 36631750, 2023). "A significant correlation was found between SPATS2 expression and tumor grades of patients with HCC." (PMID 36631750, 2023). "GSCA result also showed that SPATS2 expression was significantly increased in tumor tissues of LIHC than that in normal tissues." (PMID 36631750, 2023). "A stronger staining intensity of SPATS2 in HCC tumor tissues was observed than that in para-tumor tissues." (PMID 33391405, 2021). "The univariate analysis revealed that the ALT, AFP, maximal tumor size, microvascular invasion, tumor differentiation and SPATS2 expression were correlated with OS of HCC patients." (PMID 33391405, 2021). "The change of BCL2 and PIM1 indicated the role of SPATS2-mediated p-STAT3 in HCC tumor growth, limitless replicative potential and resistance to apoptosis." (PMID 33391405, 2021). "The AFP, maximal tumor size, microvascular invasion, tumor differentiation and SPATS2 expression were correlated with DFS of HCC patients." (PMID 33391405, 2021). "The subcutaneous xenotransplanted and orthotopic implanted tumor models were employed to further investigate the function of SPATS2 on HCC proliferation in vivo." (PMID 33037180, 2020). "The orthotopic implanted tumor model also confirmed that SPATS2 knockdown markedly decreased the HCC tumor growth with a significantly lower ratio of liver weight/body weight." (PMID 33037180, 2020). "High expression of SPATS2 was associated with vascular invasion, advanced TNM stages, tumor multiplicity, and poor survival." (PMID 33037180, 2020). "The HCC xenograft model showed that SPATS2 knockdown markedly dampened HCC tumor development, with reduced tumor volume and tumor weight." (PMID 33037180, 2020). "Our results showed that SPATS2 up-regulation was significantly correlated to tumor size (p = 0.015)." (PMID 33411682, 2020). "Additional results from GSE77509 and GSE84598 analysis showed that HCC/Portal vein tumor thrombosis or HCC/Tumor border had significantly higher expression of SPATS2 that that in normal liver." (PMID 33037180, 2020). "SPATS2 has not previously been implicated in cancer-related processes, however, RNA-seq data analysis of CRC-paired samples showed a significant up-regulation of the SPATS2 transcript in tumours versus correspondent normal tissues." (PMID 28004750, 2016). "Therefore, SPATS2 likely plays an important role in tumor immune response to regulate the functions of these immune cells." (PMID 36631750, 2023). "Recent research has found that knockdown of SPATS2 represses tumor growth and metastasis in vivo." (PMID 35077478, 2022). "In addition, the in-vivo data provided support for positive correlation with SPATS2 and tumor growth." (PMID 33391405, 2021). "Collectively, depletion of SPATS2 diminishes xenograft tumor growth potential in vivo." (PMID 33391405, 2021).
tumor (continued). "Significantly, SPATS2 was higher in tumor tissue than in normal tissue." (PMID 33391405, 2021). "Compared with normal tissues, SPATS2 expression was significantly higher in tumor specimens." (PMID 33391405, 2021). "Consistently, the IHC score of SPATS2 was remarkably higher in tumor tissues." (PMID 33391405, 2021). "In vivo, SPATS2 silencing was confirmed to impede HCC tumor development in nude mice." (PMID 33391405, 2021). "SPATS2 knockdown significantly inhibited tumor progression in vivo." (PMID 33037180, 2020). "SPATS2 was notably up-regulated in HCC tumor tissues compared to non-tumor tissues." (PMID 33411682, 2020). "Furthermore, SPATS2 is a direct target of MiR-145-5p and MiR-145-5p exerts its tumor-suppressive function via negatively regulating SPATS2 expression." (PMID 33037180, 2020). "However, SPATS2 was localized to the cytoplasm of tumor cells but also stained the basal membrane of the alveolar septum and infiltrating plasma cells." (PMID 27681076, 2016). "Notably, SPATS2 was localized to the cytoplasm of tumor cells, although we also found positive staining at the basal membrane of the alveolar septum and infiltrating plasma cells." (PMID 27681076, 2016). "Furthermore, SPATS2 knockdown suppressed HCC tumor growth and metastasis in vivo." (PMID 33037180, 2020). "The results indicate SPATS2 may function as a tumor-promoting oncogene in HCC." (PMID 33037180, 2020). "Furthermore, we find that SPATS2 upregulation is significantly correlated with tumor size." (PMID 33411682, 2020). "Together, these results suggest that SPATS2 could promote HCC tumor growth and metastasis in vivo." (PMID 33037180, 2020). "Binding of circ0001955 to miR-145-5p abolishes its tumor suppressor activity, thereby derepressing ARF6 and SPATS2." (PMID 41465470, 2025). "Another fusion is found with proximal breakpoints yielding fusion transcript SPATS2::TRA2B (21 tumor cells, 10%), and likely resulting from the same tumor genome rearrangements involving chr3 and chr12." (PMID 38464114, 2024). "The present study helps us to elucidate the significance of SPATS2 in HCC progression, especially in tumor immune microenvironment." (PMID 36631750, 2023). "Therefore, SPATS2 maybe involve in anti-tumor immune response to regulate the progression of HCC." (PMID 36631750, 2023). "The immunohistochemistry (IHC) results demonstrated that DYNC1H1, GTPBP4, PRKDC, RBM19, SF3B4, SPATS2 and TAF9 were significantly increased in HCC tumor cells compared to normal hepatocytes." (PMID 33411682, 2020). "Univariate Cox analysis also indicated that there was significant correlation between tumor size, serum AFP levels, microscopic vascular invasion, Edmondson-Steiner grade, SPATS2 up-regulation and overall survival (p < 0.05)." (PMID 33411682, 2020). "Compared with the adjacent non-tumor tissues, HCC tissues had remarkably higher expression levels of SPATS2 in all the HCC expression datasets." (PMID 33037180, 2020). "To further explore the interaction between SNHG5 and SPATS2, we investigated the SNHG5 and SPATS2 expression patterns in primary CRCs and mouse xenograft tumours." (PMID 28004750, 2016). "The correlation found in CRC samples was further confirmed by analyzing SPATS2 levels in the xenograft tumours, where knockdown of SNHG5 resulted in a significant decrease in SPATS2 mRNA levels." (PMID 28004750, 2016). "We performed an IHC analysis on paraffin-embedded tumors obtained from the same patients analyzed by CAGE above, and found clear contrasts between the staining patterns of SPATS2 and ST6GALNAC1 between AD and SCC, even in the PD form of each tumor type." (PMID 27681076, 2016). "However, the potential role of SPATS2 in HCC is yet to be elucidated, especially in tumor immune microenvironment." (PMID 36631750, 2023). "SPATS2 expression significantly correlated with sex (P=0.029), alanine aminotransferase (ALT) (P=0.001), maximal tumor size (P=0.005), microvascular invasion (P=0.007) and tumor differentiation (P<0.001)." (PMID 33391405, 2021).
tumor (continued). "Furthermore, high SPATS2 expression was positively correlated with vascular invasion, TNM stage, tumor size, and poor OS/DFS rate." (PMID 33037180, 2020).
cancer (6 papers, 2016 to 2023). A tumor composed of atypical neoplastic, often pleomorphic cells that invade other tissues. "The spermatogenesis associated serine rich 2 (SPATS2) is a member of RNA-binding protein in which the abnormal expression is linked with carcinogenesis in serval types of cancer." (PMID 36631750, 2023). "Functional enrichment analysis revealed that SPATS2 is associated with cell cycle, apoptosis and cancer cell metastasis processes in HCC." (PMID 36631750, 2023). "Since SPATS2 has been implicated in cancer-related processes, to further explore the underlying mechanism, we focused on STAT3 and its downstream pathways." (PMID 33391405, 2021). "More specifically, in the colorectal cancer cell lines HCT116, LS174T, and HT-29, SMD inhibition by long non-coding RNA SNHG5 promotes cancer cell survival via increasing the stability of several SMD target mRNAs including Spermatogenesis Associated Serin Rich 2 (SPATS2)." (PMID 34633481, 2021). "To further evaluate the functions of SPATS2, we assessed the profiles of SPATS2 expression across various types of cancers based on the results in TCGA databases." (PMID 36631750, 2023). "In conclusion, our present study explored that SPATS2 was significantly correlated with cancer progression, poor survival, epigenetic regulation and immune infiltration in patients with HCC." (PMID 36631750, 2023). "In conclusion, SPATS2 inhibition obstructs HCC by regulating the cancer cell-intrinsic hallmarks through TRIM44-STAT3 axis." (PMID 33391405, 2021). "Therefore, SPATS2 plays an important role in cell cycle, cell apoptosis, and cancer cell metastasis processes in HCC." (PMID 36631750, 2023). "Therefore, SMD-mediated degradation of SPATS2 transcripts promotes apoptosis and inhibits cancer progression." (PMID 34633481, 2021). "We found SPATS2 mRNA expression was frequently upregulated in most cancers." (PMID 33037180, 2020). "The top three significantly enriched pathways of SPATS2 included cell cycle, spliceosome, and MicoRNAs in HCC cancer." (PMID 36631750, 2023). "Q-PCR was used to reveal that the transcriptional levels of STAT3-supporting cancer cell-intrinsic hallmarks, including BCL2, MMP9, HIF-1α and PIM1, were all decreased with SPATS2 knockdown in both MHCC-97H and HCC-LM3 cell lines." (PMID 33391405, 2021). "We detected the expression of the other six genes (MCM3, SPATS2, RRM2, NT5DC2, LRRC1, and RNASEH2A) in 30 pairs of HCC and para-carcinoma tissue by immunohistochemical staining assays." (PMID 32213663, 2020).
SPATS2 also shares sentences with these, for which no sentence is quoted: adenocarcinoma of the lung (2 papers); adenoma (1); breast carcinoma (1); lung squamous cell carcinoma (1).